BARHL1 (BarH like homeobox 1)
Tractability: No criterion of Open Targets' tractability assessment is met for any kind of drug.
Gene: Protein-coding gene on chromosome 9 (132,582,606 to 132,590,252, forward strand). Ensembl gene ENSG00000125492.
Subcellular location: Nucleus
Gene Ontology:
Molecular function: sequence-specific double-stranded DNA binding; DNA-binding transcription factor activity, RNA polymerase II-specific; RNA polymerase II transcription regulatory region sequence-specific DNA binding; DNA binding; DNA-binding transcription activator activity, RNA polymerase II-specific
Biological process: regulation of transcription by RNA polymerase II; positive regulation of transcription by RNA polymerase II; regulation of DNA-templated transcription
Cellular component: chromatin; nucleus
Genetic constraint (gnomAD): Loss-of-function variants: 4 observed, 21.84 expected, observed/expected ratio (o/e) 0.18, 90% interval 0.089 to 0.42. The upper end of that interval is the gene's LOEUF score, 0.42, which puts it in group 1 of 6, group 1 being the genes least tolerant of losing a copy. Missense variants: 397 observed, 471.85 expected, observed/expected ratio (o/e) 0.84, 90% interval 0.77 to 0.91. Synonymous variants: 213 observed, 214.92 expected, observed/expected ratio (o/e) 0.99, 90% interval 0.88 to 1.11.
Homologues: Orthologues: chimpanzee BARHL1 (100% identical), macaque BARHL1 (99% identical), dog BARHL1 (99% identical), pig BARHL1 (99% identical), rabbit BARHL1 (99% identical), mouse Barhl1 (98% identical), guinea pig BARHL1 (98% identical), tropical clawed frog barhl1 (85% identical), zebrafish barhl1b (81% identical), rat Barhl1 (74% identical), zebrafish barhl1a (72% identical), Drosophila melanogaster B-H1 (39% identical), and 3 more. Paralogues in human: BARHL2 (61% identical), BARX2 (24% identical), BARX1 (22% identical).
Diseases named in the same sentence as BARHL1 in open-access papers:
BARHL1 is named in the same sentence as 19 diseases in open-access papers, as found by Europe PMC text mining. Sharing a sentence is not in itself a finding about the gene and the disease. The quoted sentences say what the papers report.
deafness (4 papers, 2019 to 2022). An inherited or acquired condition characterized by the complete loss of the ability to hear from one or both ears. "Finally, although the mutation of Barhl1 causes deafness in vivo and incapacity to differentiate into hair cell-like cells in vitro, the molecular mechanisms of Barhl1 in hair cell fate and function still keep largely unknown." (PMID 31096644, 2019). "While there is no human deafness phenotype currently associated with BARHL1 mutation, Barhl1-null mice exhibit progressive SNHL." (PMID 34342719, 2022). "This study contributes a novel genetic mechanism that Atoh1 functions as a transcriptional activator of Barhl1 through the E3 box to achieve regulation of hair cell development, which can help us to better understand the pathogenesis of deafness and find relevant cues." (PMID 31096644, 2019). "Interestingly, Barhl1 has also been identified as a deafness gene expressed in hair cells due to its key roles in the long-term maintenance of auditory hair cells." (PMID 31096644, 2019). "Moreover, the expression levels of the other nine deafness-related genes (Myo15, Gfi1, Lhx3, Barhl1, Pjvk, Tomt, Pou4f3, Tmc1, and Grxcr2) were downregulated more than 2-fold in DT-treated Prestin-hDTR mice." (PMID 30918314, 2019).
medulloblastoma (4 papers, 2016 to 2021). A malignant, invasive embryonal neoplasm arising from the cerebellum. "Barhl1 also belonged to the top-20 DEGs and genetically engineered Barhl1−/− mice model develop medulloblastoma-phenotype." (PMID 31426861, 2019). "The Transcription factor BarH like homeobox 1 (BARHL1) is overexpressed in medulloblastoma and plays a role in neurogenesis." (PMID 28956815, 2017). "This notion is supported by the high level of expression of BARHL1 in Group 3 and Group 4 medulloblastomas." (PMID 27310018, 2016). "Given the BARHL1 expression in human medulloblastomas, we anticipated that developing mouse medulloblastomas would maintain the primitive phenotype of cGNPs, including expression of the Barhl1 promoter-driven transgene, despite the increasing age of the mice." (PMID 27310018, 2016). "We chose the Barhl1 promoter for our mouse model based on its specific expression in human medulloblastomas by SAGE analysis as well as its spatial and temporal expression pattern in neonatal mouse EGL." (PMID 27310018, 2016). "This analysis identified BARHL1 as a gene exhibiting high average expression in 14 of 20 medulloblastoma libraries." (PMID 27310018, 2016). "Given the evidence of BARHL1 expression in cGNPs and its specificity for medulloblastoma tumors, we therefore examined its expression in mouse brains and in human brain tumor cell lines." (PMID 27310018, 2016). "Here we report a novel bicistronic Barhl1-TVA-eGFP/luciferase transgenic mouse model for medulloblastoma." (PMID 27310018, 2016). "Moreover, a recent extensive analysis of medulloblastoma enhancers and super-enhancers showed that BARHL1 is the most highly expressed transcription factor in Group 4 medulloblastomas and also has one of the highest number of inferred target genes." (PMID 27310018, 2016). "This Barhl1 promoter fragment drove strong luciferase expression in the medulloblastoma cells, but not in other lines, suggesting its specificity and activity in medulloblastoma." (PMID 27310018, 2016). "Thus, this database query gave us our first indication that the mouse or human BARHL1 promoter might be appropriate for use in a new transgenic model of medulloblastoma." (PMID 27310018, 2016). "In this model, a Tva transgene driven by the Barhl1 (BarH-like homeobox 1) promoter is transiently expressed in the cGNP cells of newborn mice, enabling infection of a limited number of these cells with oncogene-carrying avian viral vectors to generate medulloblastomas." (PMID 27310018, 2016). "As BARHL1 can be controlled by this super-enhancer, it seems reasonable to suspect that the BARHL1 homeobox protein may participate in specifying identity for the cells of origin for Group 3 and Group 4 medulloblastomas." (PMID 27310018, 2016). "Further support is provided by reports that Barhl1 is expressed in the cGNPs of the perinatal EGL, which are known cells of origin for some medulloblastomas." (PMID 27310018, 2016). "Recently, the BARHL1/DDX31 super-enhancer was identified as an element that activates the GFI1B oncogene when fused to it by chromosomal deletion in subsets of Group 3 and Group 4 medulloblastomas." (PMID 27310018, 2016). "In a survey of human brain tumor cell lines, we found BARHL1 expression only in the medulloblastoma cell lines (four of five examined) and not in the glioblastoma or atypical teratoid/rhabdoid tumor cell lines." (PMID 27310018, 2016).
brain tumor (2 papers, 2016 to 2017). "Apart from the importance of BARHL1 in brain homeostasis, a role of this transcription factor in brain tumor development has been reported." (PMID 28956815, 2017). "Despite the important role of BARHL1 in brain development, no studies so far have assessed BARHL1 expression in neurodegenerative disorders like AD or Parkinson’s disease (PD) or in neoplastic diseases other than brain tumors." (PMID 28956815, 2017).
Alzheimer disease (1 paper, 2017). A progressive, neurodegenerative disease characterized by loss of function and death of nerve cells in several areas of the brain leading to loss of cognitive function such as memory and language. "In this study, using a tissue microarray (TMA), we report for the first time that BARHL1 is downregulated in hormone-negative breast cancers and Alzheimer’s disease (AD)." (PMID 28956815, 2017).
breast carcinoma (1 paper, 2017). "Moreover, the immunohistochemical study also demonstrated an association between BARHL1 downregulation and estrogen hormone negative breast cancers, which favors the BARHL-ESR1 link and might explain why estrogen replacement therapy improves the cognate condition of AD patients." (PMID 28956815, 2017).
cerebellar tumor (1 paper, 2016). "Only one of the 166 non-cerebellar tumor or tissue libraries expressed BARHL1, and that was at the lowest detectable level." (PMID 27310018, 2016).
cognitive decline (1 paper, 2017). "This in silico study demonstrates an association between BARHL1 and estrogen receptor signaling, which might be related to memory and cognitive decline in AD." (PMID 28956815, 2017).
tumor (4 papers, 2016 to 2025). "The transient expression of the Barhl1 promoter predicted that the BarTeL transgene’s eGFP-luciferase fusion protein and its associated bioluminescence would decline as non-tumor-bearing mice matured." (PMID 27310018, 2016). "Within the Pax6+ clusters 0–9, based on marker gene expression and cell cycle phase, clusters 3, 4, 8 were proliferative (Ki67+) and enriched for the GCP markers Gli1, Atoh1 and Barhl1, indicating highly proliferative GCP-like tumor cells." (PMID 40766638, 2025). "Among the overexpressed genes, PTGDS (13.761-fold) had the highest log2 fold change in tumor versus non-tumor tissues, followed by TNFRSF18 (13.387-fold), glial fibrillary acidic protein (GFAP) (12.296-fold), BARHL1 (12.175-fold), and KIF26A (11.719-fold)." (PMID 30195786, 2018).
neoplastic disorders (1 paper, 2017). "However, much about the BARHL1 regulatory networks and their functions in neurodegenerative and neoplastic disorders is not yet known." (PMID 28956815, 2017).
BARHL1 also shares sentences with these, for which no sentence is quoted: amyotrophic lateral sclerosis (1 paper); cancer (1); glioblastoma (1); hearing loss (1); infection (1); neurodegenerative disease (1); rhabdoid tumor (1); soft tissue sarcoma (1); triple-negative breast carcinoma (1); tumor of the breast (1).